TMED7-TICAM2 (TMED7-TICAM2 readthrough)
Gene: Protein-coding gene on chromosome 5 (115,578,642 to 115,626,161, reverse strand). Ensembl gene ENSG00000251201.
Genetic constraint (gnomAD): Loss-of-function variants: 15 observed, 29.3 expected, observed/expected ratio (o/e) 0.51, 90% interval 0.34 to 0.79. The upper end of that interval is the gene's LOEUF score, 0.79, which puts it in group 3 of 6, group 1 being the genes least tolerant of losing a copy. Missense variants: 491 observed, 494.93 expected, observed/expected ratio (o/e) 0.99, 90% interval 0.92 to 1.07. Synonymous variants: 205 observed, 184.18 expected, observed/expected ratio (o/e) 1.11, 90% interval 0.99 to 1.25.